TTLL10 (tubulin tyrosine ligase like 10)
Description:
Inactive polyglycylase.
Synonyms: FLJ36119; TTLL5
Tractability: No criterion of Open Targets' tractability assessment is met for any kind of drug.
Gene: Protein-coding gene on chromosome 1 (1,173,880 to 1,197,940, forward strand). Ensembl gene ENSG00000162571.
Subcellular location (Human Protein Atlas): Cytosol; Plasma membrane
Pathways (Reactome):
Metabolism of proteins: Carboxyterminal post-translational modifications of tubulin
Gene Ontology:
Molecular function: protein binding; protein-glycine ligase activity
Biological process: protein polyglycylation
Cellular component: cytosol; cytoplasm
Genetic constraint (gnomAD): Loss-of-function variants: 60 observed, 59.85 expected, observed/expected ratio (o/e) 1, 90% interval 0.81 to 1.24. The upper end of that interval is the gene's LOEUF score, 1.24, which puts it in group 5 of 6, group 1 being the genes least tolerant of losing a copy. Missense variants: 954 observed, 862.42 expected, observed/expected ratio (o/e) 1.11, 90% interval 1.05 to 1.17. Synonymous variants: 403 observed, 357.25 expected, observed/expected ratio (o/e) 1.13, 90% interval 1.04 to 1.23.
Homologues: Orthologues: macaque TTLL10 (72% identical), chimpanzee TTLL10 (62% identical), pig TTLL10 (61% identical), rat Ttll10 (55% identical), mouse Ttll10 (53% identical), guinea pig TTLL10 (50% identical), tropical clawed frog TTLL10 (39% identical), zebrafish ttll10 (38% identical). Paralogues in human: TTLL6 (16% identical), TTLL13 (16% identical), TTLL7 (15% identical), TTLL4 (15% identical), TTLL3 (15% identical), TTLL11 (15% identical), TTLL8 (15% identical), TTLL9 (14% identical), TTLL2 (14% identical), TTLL1 (13% identical), TTLL12 (11% identical), KPRP (6% identical).